EPHA2 (EPH receptor A2)
Diseases named in the same sentence as EPHA2 in open-access papers (continued):
Sharing a sentence is not in itself a finding about the gene and the disease.
Sepsis (2 papers, 2022 to 2025). Sepsis is defined as life-threatening organ dysfunction caused by a dysregulated host response to infection. "Furthermore, elevated EphA2 levels are associated with poor outcomes in severe sepsis, possibly because they influence endothelial barrier breakdown and exacerbate systemic inflammation in severe sepsis." (PMID 39926431, 2025). "This consistent pattern reinforces previous research indicating that EphA2 is closely associated with sepsis progression and could serve as a potential biomarker for both the diagnosis and prognosis of patients with sepsis." (PMID 39926431, 2025). "Furthermore, non-survivors showed significantly higher median levels of plasma EphA2 than survivors, regarding EphA2 levels (898.09 vs. 475.88 pg/mL, p < 0.001), indicating that elevated EphA2 levels may be associated with worse outcomes in sepsis." (PMID 39926431, 2025). "Plasma EphA2 levels consistently increased with sepsis severity, suggesting its biomarker value for sepsis diagnosis and prognosis." (PMID 39926431, 2025). "This is because the EphA2 promotes vascular permeability and endothelial dysfunction contributing to sepsis progression; on the contrary, Del-1 suppresses excessive leukocyte recruitment and controls inflammation." (PMID 39926431, 2025). "Previous studies have shown that EphA2 activation contributes to vascular permeability and leukocyte migration, both of which are key processes in the pathophysiology of sepsis." (PMID 39926431, 2025). "In conclusion, for the diagnosis and severity of sepsis, plasma EphA2, which shows a consistent upward trend as the disease progresses, had a greater diagnostic value than plasma Del-1, which exhibits varying changes throughout the disease." (PMID 39926431, 2025). "EphA2 plays a critical role in sepsis by mediating inflammation and endothelial dysfunction." (PMID 39926431, 2025). "Vascular endothelial dysfunction is a critical factor in sepsis, and several studies suggest that EphA2 may influence inflammation by promoting endothelial injury." (PMID 39926431, 2025). "However, its anti-inflammatory properties contrast with the pro-inflammatory effects of the EphA2 during sepsis." (PMID 39926431, 2025). "Notably in this study, we observed changes in plasma EphA2 and Del-1 levels in patients with sepsis, across healthy controls, and SIRS patients." (PMID 39926431, 2025). "The Median plasma EphA2 levels increased progressively from healthy controls to SIRS and sepsis cases (154.29, 293.52, and 554.24 pg/mL; all p < 0.05)." (PMID 39926431, 2025). "In this study, we compared the plasma levels of the EphA2 and Del-1 among healthy controls, patients with SIRS, and patients with sepsis." (PMID 39926431, 2025). "Our findings showed that plasma EphA2 levels progressively increased from controls to patients with SIRS and sepsis, with higher levels corresponding to greater sepsis severity." (PMID 39926431, 2025). "The levels of both biomarkers were higher in 28-day non-survivors than in survivors, in patients with sepsis (EphA2:898.09 vs. 475.88 pg/mL, p < 0.001; Del-1:46.09 vs. 32.68 pg/mL, p = 0.193); however, only EphA2 was statistically significant." (PMID 39926431, 2025). "Furthermore, when comparing plasma EphA2 and Del-1 levels among controls, SIRS, and sepsis patients within the 20–50 years age subgroup, consistent trends were observed." (PMID 39926431, 2025). "The plasma EphA2 levels increased progressively from the controls to patients with SIRS and sepsis, with the highest levels observed in sepsis non-survivors, indicating an association with worsening prognosis." (PMID 39926431, 2025).
soft tissue sarcoma (2 papers, 2010 to 2022). A malignant neoplasm arising from muscle tissue, adipose tissue, blood vessels, fibrous tissue, or other supportive tissues excluding the bones. "We have noticed that anti-EPHA2 and anti-EPHB4 as well as anti-ephrin-B1 therapeutic agents have been explored in bone and soft tissue sarcomas, albeit they could have also been tried in the clinical setting." (PMID 35563562, 2022).
urothelial carcinoma (2 papers, 2020 to 2023). A malignant neoplasm derived from the transitional epithelium of the urinary tract (urinary bladder, ureter, urethra, or renal pelvis). "EphA2 expression in ten matched pairs of primary and metastatic lesions of urothelial carcinomas showed a high level of concordance (90% concordance) in EphA2 expression in tumor cells and tumor-associated blood vessels between primary and metastatic lesions." (PMID 33092175, 2020). "EphA2 expression was initially assessed in twenty surgical resections of urothelial carcinomas by IHC." (PMID 33092175, 2020). "Our survey of patient tumor samples supports the prognostic relevance of EphA2 expression in urothelial carcinomas." (PMID 33092175, 2020). "Interestingly, immunohistochemical analysis of progranulin and EphA2 expression showed progranulin and EphA2 upregulation in urothelial carcinoma tissues." (PMID 36980592, 2023).
acute coronary syndrome (1 paper, 2020). Signs and symptoms related to acute ischemia of the myocardium secondary to coronary artery disease. "Results showed that serum EphA2, VCAM-1, and Hcy levels in acute coronary syndrome patients were significantly higher than those in chronic coronary syndrome patients (p = 0.000; p = 0.000; p = 0.033, respectively)." (PMID 33510642, 2020).
acute kidney injury (1 paper, 2022). Sudden and sustained deterioration of the kidney function characterized by decreased glomerular filtration rate, increased serum creatinine or oliguria. "Given that EphA2 promotes inflammation during oral C. albicans infection, we assessed the contribution of EphA2 in a mouse model of zymosan (β-glucan) - induced acute kidney injury (AKI), in which immune cells and inflammation exert essential roles in kidney damage." (PMID 36138043, 2022).
adrenocortical carcinoma (1 paper, 2021). "Furthermore, data from bioinformatical analyses have implicated that ANAX1, CYR61, and VIM are mainly associated with the development of PAAD and GBM, while CEACAM1 and EPHA2 are associated with adrenocortical carcinoma." (PMID 34908921, 2021).
albinism (1 paper, 2020). A congenital disorder characterized by partial or complete absence of melanin pigment in the eyes, hair, or skin. "The genes identified for MAC were KMT2D, MAB2IL2, ALDH1A3; ASDA were KERA, PAX6, MYOC, TGFBI, and SLC4A11; congenital cataract were CRYBB2, EPHA2, HSF4 and BCOR; infantile nystagmus were CACNA1A and FRMD7; and albinism were OCA2, GPR143, HPS6 and SLC38A8." (PMID 32830442, 2020).
arteriosclerosis (1 paper, 2020). A vascular disorder characterized by thickening and hardening of the walls of the arteries. "For the first time, we investigated the levels of EphA2, PGRN, VCAM1, and Hcy in arteriosclerosis patients and evaluated the function of PGRN and EphA2 in Hcy-induced injury of ECs." (PMID 33510642, 2020). "This study aimed to investigate the levels of EphA2, PGRN, and Hcy in arteriosclerosis patients and to evaluate how PGRN and EphA2 exert their function in EC with Hcy-induced injury." (PMID 33510642, 2020). "We aimed to investigate the levels of progranulin (PGRN), Eph-receptor tyrosine kinase-type A2 (EphA2), vascular cell adhesion molecule-1 (VCAM-1), and Hcy in patients with arteriosclerosis and investigate their functions in Hcy-injured human umbilical vein endothelial cells (HUVECs)." (PMID 33510642, 2020).
brain infarct (1 paper, 2013). "Neurological deficit scores and brain infarct volumes were significantly less in EphA2−/− mice compared with WT controls." (PMID 23308246, 2013).
candidiasis (1 paper, 2022). Infection with the organism Candida. "The β-glucan receptor ephrin type-A 2 receptor (EphA2) is required to initiate mucosal inflammatory responses during oral Candida infection." (PMID 36138043, 2022). "Collectively, this data suggest that EphA2 promotes ferroptotic cell death via an extrinsic pathway during candidiasis." (PMID 36138043, 2022). "To determine if increased IL-23 levels contribute to tolerance of Epha2–/– mice during candidiasis we depleted IL-23 p19 during infection." (PMID 36138043, 2022). "IL23 p19 depletion decreased survival of Epha2–/– mice during candidiasis, increased renal fungal burden, and exaggerated renal ferroptosis." (PMID 36138043, 2022). "EphA2 reduces migration of and IL-23 secretion from dendritic cells (DCs), while IL-23 receptor signaling inhibits host cell ferroptosis during candidiasis." (PMID 36138043, 2022). "While kidney sections of WT mice showed strong lipid peroxidation, sections of Epha2–/– mice had low levels of ferroptosis suggesting that during candidiasis host cells undergo excessive lipid peroxidation although anti-ferroptotic mechanisms are upregulated in myeloid cells." (PMID 36138043, 2022).
Cerebellar medulloblastoma (1 paper, 2021). "Prominent EphA2 expression and ephrinA5-Fc binding was likewise observed for DAOY cells, which represents a human tumorigenic cerebellar medulloblastoma cell line (ATCC® HTB-186TM)." (PMID 33572758, 2021).
Cerebral ischemia (1 paper, 2013). Restriction of arterial blood supply to the brain associated with insufficient oxygenation to support the metabolic requirements of the tissue. "Cerebral ischemia was induced in male C57Bl6/J wild-type (WT) and EphA2-deficient (EphA2−/−) mice by middle cerebral artery occlusion (MCAO; 60 min), followed by reperfusion (24 or 72 h)." (PMID 23308246, 2013).
cervical squamous cell carcinoma (1 paper, 2021). A squamous cell carcinoma arising from the cervical epithelium. "The high expression of EphA2 and EphrinA‐1 protein in cervical squamous cell carcinoma indicates a poorer overall survival, but the underlying mechanism remains largely unknown." (PMID 33586348, 2021).
chlamydial infection (1 paper, 2015). "The rapid and strong activation of EphA2 by chlamydial infection and the association of EphA2 with inclusion during the replicative phase of the developmental cycle suggested that EphA2 is required for chlamydial development, probably by signaling via PI3K." (PMID 25906164, 2015). "This profile of EphA2 surface display and receptor upregulation induced by chlamydial infection is strikingly different from that observed after Ephrin-A1 stimulation." (PMID 25906164, 2015). "Several lines of evidence support a crucial role of EphA2 in PI3K activation during chlamydial infection." (PMID 25906164, 2015). "Phosphorylation of EphA2 at Ser897 (pEphA2), indicative of receptor activation, was detected close to adhering EB during the entry phase of chlamydial infection, suggesting that interaction of EB induced receptor activation." (PMID 25906164, 2015). "Thus, we show that EphA2 is an undiscovered important surface and intracellular signaling receptor that is crucial for chlamydial infection and development." (PMID 25906164, 2015). "Thus, EphA2 is involved in fundamental processes of chlamydial infection." (PMID 25906164, 2015). "The dose-dependent downregulation of mid phase-chlamydial infection by dasatinib, which can inhibit the activity of EphA2, Src, BCR-Abl, KIT and PDGFR, did not correlate well with the downregulation of the PI3K pathway." (PMID 25906164, 2015). "Activation of PI3K is, however, not completely dependent on activated EphA2 during chlamydial infection which indicates a possible role of other PI3K-inducing pathways." (PMID 25906164, 2015). "However, a kinase inactive EphA2 mutant also affected PI3K activation and Ctr infection, demonstrating a role of the EphA2 kinase activity in chlamydial infection." (PMID 25906164, 2015).
chronic pancreatitis (1 paper, 2016). A chronic inflammatory process causing damage and fibrosis of the pancreatic parenchyma. "The EphA2 antibody did n't appear to stain normal pancreatic tissue, whereas staining of surviving acinar tissue and the stroma of chronic pancreatitis tissue was evident." (PMID 26959746, 2016). "In chronic pancreatitis tissue, we found EphA2 staining in surviving acinar tissue, and also in some unknown tissue with characteristic islets morphology." (PMID 26959746, 2016).
colorectal adenoma (1 paper, 2026). An adenoma that arises from the colon or rectum. "Notably, several TAAs currently evaluated in clinical trials, such as EphA2 and Survivin for GBM and MUC1 for colorectal adenoma, are highly expressed in some normal tissues at the mRNA level without evidence for the induction of autoimmune responses." (PMID 41436600, 2026).
corneal infection (1 paper, 2017). A viral or bacterial infectious process affecting the cornea. "We hypothesize a possible involvement of EphA2 with macropinocytotic activation leading to corneal infections." (PMID 28118670, 2017).
craniorachischisis (1 paper, 2017). Craniorachischisis is the most severe form of neural tube defect in which both the brain and spinal cord remain open to varying degrees. "The defect is selective enough not to phenocopy craniorachischisis, yet its caudal and anterior neuropores remain remarkably open in the areas where EphA2 and EphA4 would be expressed in the wildtype." (PMID 29312933, 2017).
cyclopia (1 paper, 2017). "Furthermore, expression of EphA2 in the notochord could explain a potential role between Sonic hedgehog and the EphA receptor family seeing that the double heterozygotes in our study display cyclopia." (PMID 29312933, 2017).
disseminated candidiasis (1 paper, 2022). Systemic candidiasis occurs when Candida yeast enters the bloodstream and may spread (becoming disseminated candidiasis) to other organs, including the central nervous system, kidneys, liver, bones, muscles, joints, spleen, or eyes. "Together, this data suggest that EphA2 promotes inflammation to accelerate disease progression during disseminated candidiasis." (PMID 36138043, 2022). "Since EphA2 is expressed on both stromal and hematopoietic cells, we generated bone marrow (BM) chimeric mice and determined their resistance to disseminated candidiasis." (PMID 36138043, 2022). "How EphA2 contributes to disease progression in specific host cell types during disseminated candidiasis is under active investigation." (PMID 36138043, 2022). "These experiments suggested that EphA2 is critical to promote renal inflammation during disseminated candidiasis." (PMID 36138043, 2022). "Here we report that EphA2 promotes renal immunopathology during disseminated candidiasis." (PMID 36138043, 2022). "Although the function of this novel β-glucan receptor EphA2 is well established during oral mucosal C. albicans infection, the role of EphA2 during disseminated candidiasis is unknown." (PMID 36138043, 2022). "Here, we show that EphA2 promotes immunopathology during disseminated candidiasis." (PMID 36138043, 2022).
ductal carcinoma (1 paper, 2011). "We found an inverse correlation between EphA2 and ephrin-A1 protein expression in a significant number of invasive ductal carcinoma samples in lymph node relative to normal breast and ductal carcinomas confined to the breast, which co-express both." (PMID 21935409, 2011). "By contrast, a disproportionate number of metastatic ductal carcinoma samples that were EphA2 positive displayed little or no ephrin-A1 expression." (PMID 21935409, 2011).
endometrial tumor (1 paper, 2021). "Specifically, we found that blocking of EphA2 expression resulted in significant inhibition of endometrial tumor killing mediated by Vδ1 γδ T cells." (PMID 34691070, 2021). "We showed high expression of the EphA2 receptor on KLE and RL-95 endometrial tumor cell lines, and these were used as targets in the EphA2 blocking studies." (PMID 34691070, 2021). "Second, we used the EPHA2 small-molecule inhibitor ALW-II-41-27 on KLE endometrial tumor cells and also showed specific lysis significantly reduced at both 5:1 and 10:1 E:T ratios." (PMID 34691070, 2021). "To validate these findings, we then tested the in vitro effects of the EPHA2 small-molecule inhibitor ALW-II-41-27 on KLE endometrial tumor cells." (PMID 34691070, 2021).
Fibroadenoma (1 paper, 2011). A benign tumor of the breast characterized by the presence of stromal and epithelial elements. "A significantly higher percentage of human invasive ductal carcinoma samples displayed expression of EphA2, EphA4, or EphA7 in tumor epithelium relative to ‘normal’ samples (normal/hyperplastic or fibroadenoma), which were largely negative." (PMID 21935409, 2011).
follicular thyroid cancer (1 paper, 2019). "Therefore, we may hypothesize that EPHA2 signalling regulates cell adhesion and spreading in follicular thyroid cancer cells in a FAK/Src-dependent manner." (PMID 31060342, 2019).
gallbladder carcinoma (1 paper, 2023). "As VM signaling-related markers, ephrin type-A receptor 2 (EphA2), FAK, and paxillin overexpression in human gallbladder carcinoma GBC-SD cells promote tumor growth and VM." (PMID 37175948, 2023).
gastric tumor (1 paper, 2018). "Using this approach, the combination of siRNA (small interfering RNA) of EphA2, which inhibits its expression and miR-338 suppressed gastric tumor cells growth." (PMID 30581418, 2018).
hearing loss (1 paper, 2021). "Sequencing of the EPHA2 gene in 40 Japanese patients with hearing loss and monoallelic mutations in the SLC26A4 gene who were negative for the CEVA haplotype led to the identification of two individuals with potentially pathogenic EPHA2 sequence variants." (PMID 34562878, 2021).
hepatitis C virus infection (1 paper, 2021). A viral infection caused by the hepatitis C virus. "On the other hand, it has been reported that in hepatitis C virus infection, multiple receptor molecules, including SR-B1, low-density lipoprotein receptor, CD81, claudin-1, occluding, epidermal growth factor receptor, and EphA2 are involved in its process." (PMID 34372540, 2021).
Hyperglycemia (1 paper, 2014). An increased concentration of glucose in the blood. "We conclude that EphA2-mutant mice are more prone to hyperglycemia-induced increased injury, decreased survival, and worsened LV remodeling due to impaired wound healing." (PMID 25166508, 2014).
Hypoglycemia (1 paper, 2021). A decreased concentration of glucose in the blood. "In control subjects, HSPB1, SMAD3 and HSPA1A decreased significantly, whilst MAPKAPK5 increased significantly in controls from baseline to hypoglycemia whilst, in T2D, PPP3CA increased and EPHA2 decreased." (PMID 34426634, 2021).
inflammatory bowel disease (1 paper, 2023). A spectrum of small and large bowel inflammatory diseases of unknown etiology. "Among these genes, Dusp4, Epha2, Atp11a, and Tns4 are reported to be overexpressed in human CRC, while the expression of Thbs1 is increased in patients with inflammatory bowel disease." (PMID 37296911, 2023).
insulinoma (1 paper, 2019). "To better understand the molecular underpinnings of EphA2/A3 upregulation, we next tested if depletion of Ift88 mRNA resulted in similar EphA3 upregulation in an insulinoma cell line, Min6m921." (PMID 31831727, 2019).
invasive carcinoma (1 paper, 2023). A carcinoma that is not confined to the epithelium, and has spread to the surrounding stroma. "Indeed, the correlation between the EphA2-NF value and pancreatic duct size was analyzed in patients with IPMN, including invasive carcinoma cases." (PMID 37712876, 2023).
ischemia reperfusion injury (1 paper, 2010). Adverse functional, metabolic, or structural changes in ischemic tissues resulting from the restoration of blood flow to the tissue (reperfusion), including swelling; hemorrhage; necrosis; and damage from free radicals. "In a mouse model of ischemia-reperfusion injury (IRI), renal expression of EphA2 mRNA was markedly increased and EphA2 protein was detected in distal tubules." (PMID 20687922, 2010).